ABCG2 (ATP binding cassette subfamily G member 2 (JR blood group))
Diseases named in the same sentence as ABCG2 in open-access papers (continued):
Sharing a sentence is not in itself a finding about the gene and the disease.
hyperuricemia (continued). "Recently, we and another group reported that the ATP-binding cassette transporter subfamily G member 2 (ABCG2)/breast cancer resistance protein (BCRP) mediates physiological secretion of urate and that hereditary dysfunction of ABCG2 increases the risk of hyperuricemia and gout." (PMID 30042379, 2018). "[36•] reported that FEUA is lower in those with the ABCG2 variants associated with hyperuricemia." (PMID 27105641, 2016). "In addition, as a member of the ATP-binding cassette superfamily of membrane transporters, ABCG2 rs2231142 also act as a uric acid transporter and it is well-known that the dysfunction of ABCG2 can cause hyperuricemia." (PMID 25617895, 2015). "Additionally, the ABCG2 population-attributable percent risk for hyperuricemia has been reported to be 29.2%, which is much higher than for those with more typical environmental risks such as BMI ≥ 25.0 (18.7%), heavy drinking (15.4%), and age ≥ 60 years old (5.74%)." (PMID 33669292, 2021). "Besides renal excretion, recent findings demonstrated physiological and pathophysiological roles of ABCG2 on intestinal urate excretion in humans, where the degree of intestinal ABCG2 dysfunction showed strong associations with the severity of hyperuricemia in the setting of end-stage renal disease." (PMID 30181573, 2018). "We evaluated the effect size on SUA and population attributable fractions (PAFs) for hyperuricemia progression based on factors, including ABCG2 function, BMI, alcohol consumption, age, and menstrual status (in women)." (PMID 42310200, 2026). "Collectively, these findings establish ABCG2 as a core genetic determinant of hyperuricemia across populations." (PMID 41601955, 2026). "This study identified vitexin as one of the primary active flavonoids in hawthorn that ameliorate hyperuricemia by targeting the PPARγ/ABCG2 pathway." (PMID 42255677, 2026). "In the tested female sample, the PAF for hyperuricemia due to ABCG2 dysfunction (32.8%) exceeded those for overweight/obesity (19.5%) and aging (28.7%)." (PMID 42310200, 2026). "Another study employing ABCG2 knockout mouse models have demonstrated that ABCG2 dysfunction leads to reduced extrarenal urate excretion, consequently inducing hyperuricemia." (PMID 40365321, 2025). "The ABCG2 gene encodes the critical transporter BCRP (breast cancer resistance protein), whose dysregulation contributes to hyperuricemia." (PMID 40282409, 2025). "When XOD or ABCG2 was inhibited in the SV, ferritinophagy was attenuated, and the inhibition of hair cell activity by hyperuricemia was reversed." (PMID 40041973, 2025). "PAF for dysfunctional ABCG2 variants reached approximately 30% in males, females, and in both populations, indicating that about 30% of hyperuricemia patients in the Japanese population originate from ABCG2 dysfunction." (PMID 41452549, 2025). "Investigation into hyperuricemia-induced renal tissue in mice revealed that PO exerts efficacious synergistic regulation over UA excretion protein ABCG2 and urate transporters URAT1 and GLUT9, thereby preserving murine UA homeostasis." (PMID 39458543, 2024). "Probiotics and prebiotics have been shown to ameliorate hyperuricemia in mice by modulating the gut microbiota and increasing the expression of UA exporter genes such as ABCG2 and SLC2A9." (PMID 38674582, 2024). "ATP-binding cassette subfamily G member 2 (ABCG2) is identified as a high-capacity urate transporter and its dysfunction is linked to elevated SUA levels and an increased risk of hyperuricemia." (PMID 38317153, 2024). "UA drives excretion through the activation of signaling cascades involving NLRP3, PI3K/Akt and MAPK, leading to the augmentation of PDZK1 and ABCG2 expression, thereby mitigating the effects of hyperuricemia." (PMID 38094893, 2023). "Three uric acid transporters, URAT1, GLUT9, and ABCG2, play key roles in the regulation of serum uric acid, and their dysfunctions lead to dysuricemia (hypouricemia and hyperuricemia)." (PMID 37238926, 2023).
hyperuricemia (continued). "B. xylanisolvens reduces serum uric acid concentrations in hyperuricemia in the Goslings' model, and it can up-regulation ABCG2 mRNA expression in the kidney and down-regulation XDH mRNA expression in the liver." (PMID 37455728, 2023). "ABCG2 dysfunction is a common mechanism of hyperuricemia resulting from decreased gut urate excretion." (PMID 38082308, 2023). "The results indicated that MOL-FP accelerated the excretion of UA and effectively reduced the serum UA level in hyperuricemia mice by up-regulating the expression of ABCG2 and down-regulating the expression of URAT1 and GLUT9." (PMID 36500329, 2022). "More and more studies have found that ABCG2 plays an important role in intestinal uric acid excretion and the pathogenesis of hyperuricemia." (PMID 35281005, 2022). "It is possible that ABCG2 increases its expression in blood and tissues in a state of hyperuricemia, trying to eliminate sUA in different cell types." (PMID 35505381, 2022). "Consistently, the serum uric acid level is increased in ABCG2 gene knockout mice in a established a hyperuricemia mouse model by using the urinase inhibitor potassium oxonate." (PMID 35281005, 2022). "Our data suggest that leukocytes of patients respond to the presence of hyperuricemia and comorbidities, expressing ABCG2 and IL-1β genes differentially compared to normouricemic and nondisease states." (PMID 35505381, 2022). "However, decreased ABCG2 function may enhance the risk of hyperuricaemia, genetically." (PMID 34335246, 2021). "There is a large amount of genetic evidence suggesting that ABCG2 is clearly related to hyperuricemia." (PMID 34144706, 2021). "Inulin supplementation can effectively alleviate hyperuricemia, increase the expressions of ABCG2 in intestine, and downregulate expression and activity of hepatic XOD (xanthine oxidase) in KO mice." (PMID 33104864, 2021). "For clinical practice, our findings suggest a need for further discussion about the potential benefits of urate-lowering therapy after a diagnosis of hyperuricemia in pediatric-onset patients with ABCG2 dysfunction." (PMID 33669292, 2021). "A previous study showed that in the context of extra-renal underexcretion hyperuricemia, a genetic dysfunction of ABCG2 increased SUA levels and apparent urinary urate excretion, which was coupled with decreased intestinal urate excretion." (PMID 33669292, 2021). "In addition, impaired intestinal urate excretion induced by the orthologous murine Q140K mutation or complete ABCG2 knockout may explain hyperuricemia despite unaltered renal urate excretion in the respective mouse models as well as in human individuals carrying the Q141K polymorphism." (PMID 34206432, 2021). "Administering estradiol benzoate (EB) to both male hyperuricemic mice and female mice after removing the ovaries confirmed the urate-lowering effect of estradiol, and hyperuricemia and estradiol upregulated the expression of intestinal ABCG2." (PMID 34144706, 2021). "Hosomi et al35 used potassium oxonate‐induced rat models of hyperuricemia to study intestine circulation and showed that the ABCG2 inhibitor acridine inhibits ABCG2‐mediated intestinal secretion of uric acid." (PMID 34251052, 2021). "Urate transporters related to the secretion of uric acid also changed significantly in hyperuricemia mice, the expression of ABCG2 and OAT1 was downregulated from the 3rd day, and NPT1 was downregulated from the 7th day." (PMID 32707836, 2020). "Genetic variants of urate transporters such as ABCG2, URAT1, GLUT9 in human are a common cause of clinical hyperuricemia, which is harder to control and progress easily." (PMID 32116724, 2020). "ABCG2 is also expressed in intestine, and many patients with hyperuricemia lost the expression of ABCG2 in intestines." (PMID 32245084, 2020). "ABCG2 dysfunction results in extra-renal urate under-excretion and is a common mechanism of hyperuricemia." (PMID 31744152, 2019).
hyperuricemia (continued). "Renal underexcretion of urate, due to the dysfunction of the ABCG2 high-capacity urate exporter, is a major contributor to hyperuricemia." (PMID 30894219, 2019). "This essentially includes our recent findings, as we serendipitously identified febuxostat, a well-used agent for hyperuricemia as a strong ABCG2 inhibitor, that possesses some promising potentials." (PMID 30890942, 2019). "In the present study, the results showed that the expression levels of GLUT9 and URAT1 were significantly increased in the hyperuricemia group, whereas the expression levels of ABCG2 and OAT1 were significantly decreased." (PMID 31185695, 2019). "Taken together, our findings strongly suggest the need for a discussion about the potential benefits of urate-lowering therapy after a diagnosis of hyperuricemia in pediatric-onset patients with ABCG2 dysfunction." (PMID 30894219, 2019). "The protein expression of ABCG2 was significantly increased in the low-dose fucoxanthin group and the combination group compared with the hyperuricemia group." (PMID 31185695, 2019). "Recently, this dysfunctional SNP was revealed to result in hyperuricaemia and decreased intestinal urate excretion, according to research on ABCG2-knockout mice and hyperuricaemic patients." (PMID 31367212, 2019). "The association between VDD and hyperuricemia can be postulated by UA inhibition of hepatic 25-hydroxylation or PTH-induced ABCG2 down-regulation in the intestine and proximal renal tubules, which results in hyperuricemia." (PMID 31491937, 2019). "However, recent studies substantiated that the mutations of ABCG2 could cause hyperuricemia." (PMID 29246027, 2017). "ABCG2, another ATP-binding cassette of half-transporter protein, is identified in the researches of hyperuricemia and gout in gene level." (PMID 29246027, 2017). "Pathophysiologically, in end-stage renal disease patients, the degree of intestinal ABCG2 dysfunction strongly affects the severity of hyperuricemia because urate excretion almost all depends on intestinal excretion via ABCG2." (PMID 27571712, 2016). "Human genetic analyses and animal model studies have demonstrated that ABCG2 dysfunction plays an important role in the pathogenesis of hyperuricemia." (PMID 24857923, 2014). "While ABCG2 dysfunction is a common mechanism of hyperuricemia." (PMID 40100069, 2025). "Among these, the upregulation of ZBTB20, a transcriptional repressor of the urate transporter ABCG2, may explain the persistent hyperuricemia observed in CGA by impairing renal urate excretion." (PMID 41511324, 2025). "Our study provides the first evidence that METTL3 regulates uric acid excretion by controlling the m6A levels of ABCG2 through the binding of IGF2BP2, and inhibiting METTL3 can effectively alleviate kidney damage caused by hyperuricemia, showing potential as a therapy for HN." (PMID 40100069, 2025). "Accordingly, the traditional “overproduction type” of hyperuricemia has been relabeled as ‘renal overload type,’ which encompasses both urate overproduction and extra-renal underexcretion (e.g., reduced intestinal elimination due to ABCG2 dysfunction)." (PMID 41329531, 2025). "Dysfunction of ABCG2 is a common mechanism of hyperuricemia, while upregulation of ABCG2 could alleviate HN." (PMID 40100069, 2025). "The antioxidant effects of molybdenum may have prevented ABCG2 inhibition by ROS, thereby maintaining uric acid excretion and preventing the development of hyperuricemia." (PMID 39088565, 2024). "However, hyperuricemic patients with varying degrees of ABCG2 dysfunction, categorized by genotypes of dysfunctional SNPs, exhibit hyperuricemia characterized by urate overproduction." (PMID 39191722, 2024). "We found that our newly isolated Bacteroides xylanisolvens could inhibit hyperuricemia in goslings by up-regulating ABCG2 mRNA expression in the kidney and down-regulating XDH mRNA expression in the liver." (PMID 37455728, 2023).
hyperuricemia (continued). "A more complete study could show if there are groups of patients who strongly increase the expression of ABCG2 in acute attack conditions, who maintain subclinical inflammation, with hyperuricemia for a long time." (PMID 35505381, 2022). "PTH may downregulate the expression of the urate exporter ABCG2 in intestinal and renal and suppress the urate excretion, which in turn could lead to hyperuricemia." (PMID 36583002, 2022). "ABCG2 and PKD2 were found to have epistatic interactions, and two SNP pairs (rs2728121:rs1481012 and rs2728121:rs2231137) were mainly identified as associated with the serum urate concentration or risk of hyperuricemia." (PMID 35813212, 2022). "Another putative mechanism is that BPA may downregulate uric acid transporters in the kidney and intestine, such as adenosine triphosphate binding cassette subfamily G member 2 (ABCG2), thereby contributing to hyperuricemia." (PMID 35709251, 2022). "Bergenin, a C-glucoside of 4-O-methyl gallic acid isolated from several medicinal plants, has been shown to reduce serum urate levels in a hyperuricemia-induced mouse model by elevating Abcg2 expression in both the kidney and intestine and by suppressing Slc2a9 expression in the kidney." (PMID 36483739, 2022). "Berberrubine has also been shown to reduce hepatic XOD activity, downregulate the expression of Glut9 and Urat1 and upregulate the expression of Oat1/3 and Abcg2 at both the protein and mRNA levels in mice with hyperuricemia as well as to suppress activation of the JAK/STAT3 signaling pathway." (PMID 36483739, 2022). "Urate transporters GLUT9 and in particular ABCG2 are highly expressed in intestinal epithelial cells and may thus represent interesting new pharmacological targets for the treatment of hyperuricemia." (PMID 34206432, 2021). "One of the main causes of hyperuricaemia is not true overproduction of UA, but insufficient excretion of extra renal UA due to common ABCG2 dysfunction." (PMID 34335246, 2021). "The immunohistochemical results of HUA mouse kidneys and intestinal tracts suggested that hyperuricemia increased intestinal ABCG2 expression and that estradiol could further upregulate the expression of ABCG2 in the intestine." (PMID 34144706, 2021). "Kannangara and colleagues revealed that the ABCG2 141 K variant and the fractional renal clearance of urate contribute strongly but independently to hyperuricemia, which provided further evidence of a significant contribution of ABCG2 to extrarenal clearance of urate." (PMID 34144706, 2021). "Similarly, decreased intestinal urate elimination and hyperuricemia development resulted from the knockout of the ABCG2 transporter (Abcg2 null mice)." (PMID 33330529, 2020). "A reduced expression of BCRP/ABCG2 in TECs induced by hyperuricemia may promote MSU crystal deposition in TECs and the renal interstitium, resulting in substantial renal damage." (PMID 32685502, 2020). "Effects of rs2231142 (in ABCG2) on hyperuricemia were assessed (N = 5)." (PMID 33087043, 2020). "Therefore, ABCG2 dysfunction contributes to the pathogenesis in both renal overload hyperuricemia and renal underexcretion hyperuricemia." (PMID 31491937, 2019). "Another study also hypothesized that the degree of ABCG2 dysfunction in the intestine strongly affects the severity of hyperuricemia." (PMID 31891613, 2019). "Indeed, urate transporter genes such as SLC22A12 (also known as URAT1), SLC2A9 (GLUT9), and ABCG2 (BCRP) have been markedly associated with SUA, hyperuricemia, and gout." (PMID 30993211, 2019). "Our study found that ABCG2 contributed not only to hyperuricemia but also to gouty inflammation." (PMID 29453348, 2018). "Therefore, we evaluated ABCG2 expression in the ileal segment and found that hyperuricemia induced a 200% increase in its expression, while F1 and F2 treatments prevented this effect." (PMID 30142173, 2018).
hyperuricemia (continued). "Thus, it was supposed that the degree of intestinal ABCG2 dysfunction strongly affects the severity of hyperuricemia in hemodialysis patients, as was shown by multiple regression analysis in the present study." (PMID 27571712, 2016). "GWAS studies show that ABCG2, NPT1, and NPT4 are associated with hyperuricemia and gout." (PMID 27105641, 2016). "Therefore, it is clearly possible that the degree of renal ABCG2 dysfunction affects the severity of hyperuricemia in gastroenteritis patients, as was first shown by linear regression analysis in acute period gastroenteritis patients in the present study." (PMID 27571712, 2016). "In light of these findings, although further studies would be necessary because of the limited sample size in this study, we proposed a physiological model of urate excretion via ABCG2 in humans, and a pathophysiological model of hyperuricemia in intestinal and renal diseases." (PMID 27571712, 2016). "However, the results of both human and mouse experiments suggest that the hyperuricemia induced by the ABCG2 Q141K polymorphism is not caused by a significant effect on renal urate excretion, but is likely to be triggered by different mechanism." (PMID 34206432, 2021). "Additionally, it is still unknown whether FPS can regulate the expression of intestinal ABCG2, and other urate transporters, in hyperuricemia animals." (PMID 33922488, 2021). "Since esculetin and fraxetin restored the expressions of transporters of uric acid in the kidney, such as OAT1 and ABCG2, osthol might act on these transporters to improve hyperuricemia, since osthol presents the basic chemical structure of coumarins, similar to esculetin and fraxetin." (PMID 30388753, 2018). "Therefore, in case of ABCG2 dysfunction, the subjects have hyperuricemia first by renal urate overload and intestinal urate under-excretion; and then increased release of IL-1β (by macrophages) and IL-8 (by ECs) invoke further neutrophilic recruitment and gouty flare." (PMID 29453348, 2018). "This showed that ABCG2 mRNA expressions in hyperuricemia rats decreased significantly to 33.85% and 42.62% in jejunum and ileum respectively, and ABCG2 protein expressions by western blotting in them decreased markedly to 67.08% and 74.32% in hyperuricemia rats." (PMID 28630638, 2017). "Therefore, the degree of renal ABCG2 dysfunction clearly affects the severity of hyperuricemia." (PMID 27571712, 2016). "Thus, it is possible that increasing ABCG2 function could contribute to decreasing SUA levels in patients with hyperuricemia." (PMID 28082903, 2016). "Evidence from another animal study supports that CGA increases intestinal uric acid excretion by affecting the levels of intestinal urate transporters (ABCG2, GLUT9), combating hyperuricemia." (PMID 40821993, 2025). "The induction of the hyperuricemia model with hypoxanthine and potassium oxonate in mice resulted in a significant decrease in the expression of OAT1, ABCG2 and OCT2 (p < 0.001)." (PMID 41009565, 2025). "Hyperuricemia has a strong genetic component (40%–70%): related genes include SNPs in SLC22A12, ABCG2, HNF1A, and HNF4A." (PMID 41195208, 2025). "Therefore, ABCG2 may be a putative target for the treatment or prevention of hyperuricemia." (PMID 39275356, 2024). "In recent years, the OAT1, URAT1, ABCG2, and GLUT9 have become potential targets for hyperuricemia treatment." (PMID 37124197, 2023). "The macroporous resin extract of Dendrobium officinale leaves has been reported to reduce serum urate levels in rats with fructose- and PO-induced hyperuricemia by inhibiting XOD activity and regulating the expression of Abcg2, Urat1, and Glut9." (PMID 36483739, 2022). "Benzbromarone also inhibits urate transport via ABCG2, as does febuxostat, suggesting that URAT1 inhibitors are more potent in lowering serum urate than XOR inhibitors in hyperuricemia of reduced urate excretion type." (PMID 36714585, 2022).